ENSG00000285777 (novel protein)
Gene: Protein-coding gene on chromosome 1 (173,596,060 to 173,669,837, reverse strand). Ensembl gene ENSG00000285777.
Genetic constraint (gnomAD): Missense variants: 234 observed, 289.36 expected, observed/expected ratio (o/e) 0.81, 90% interval 0.73 to 0.9. Synonymous variants: 78 observed, 96.86 expected, observed/expected ratio (o/e) 0.81, 90% interval 0.67 to 0.97.